RNU7-103P (RNA, U7 small nuclear 103 pseudogene)
Gene: Small nuclear RNA gene on chromosome 12 (589,530 to 589,589, reverse strand). Ensembl gene ENSG00000238370.
Homologues: Orthologues: chimpanzee U7 (97% identical), macaque U7 (85% identical). Paralogues in human: RNU7-48P (87% identical), RNU7-88P (87% identical), RNU7-50P (85% identical), RNU7-65P (85% identical), RNU7-113P (83% identical), RNU7-2P (83% identical), RNU7-55P (83% identical), RNU7-57P (83% identical), RNU7-13P (82% identical), RNU7-172P (82% identical), RNU7-197P (82% identical), RNU7-30P (82% identical), and 142 more.